IL4 (interleukin 4)
Diseases named in the same sentence as IL4 in open-access papers (continued):
Sharing a sentence is not in itself a finding about the gene and the disease.
COVID-19 (continued). "At least three further pathways indicate a strong overlap between neurodegeneration, COVID-19 and inflammation, such as »Interleukin-4 and interleukin-13 signaling«, »Cytokine signaling in immune system«, and »Signaling by interleukins«." (PMID 37008787, 2023). "UCB mesenchymal cells reduce inflammation, including cytokine storms in COVID-19 patients, as indicated by decreased IL-4, IL-6, and IL-10 levels." (PMID 37763198, 2023). "It is generally believed that the imbalance in Th1 and Th2 responses in COVID-19 patients triggers a cellular inflammatory storm, and increase the levels of inflammatory mediators such as interleukin IL-4, IL-10, and IL-6 in tissue samples." (PMID 37180704, 2023). "In the severe COVID-19 group, we observed a hyperinflammatory state, as judged by increased concentration of cytokines (IL-1α, IL-4, IL-6, IL-10 and IL-17A), chemokines (IP-10 and MIP-1β), and adhesion markers (E-selectin and ICAM-1)." (PMID 37441066, 2023). "For instance, we found enrichment of JAK-STAT signaling, IL-4 signaling, and IL-6 signaling in COVID-19 patients." (PMID 36992700, 2023). "Elevated levels of serum type 2 cytokines, including IL-4 and IL-13, were found to be predictive of life-threatening COVID-19 in hospitalized patients." (PMID 37631998, 2023). "A phase IIa trial demonstrated that dupilumab reduces the probability of admission to the intensive care unit for patients with moderate to severe COVID-19 and improves the survival rate of patients by disabling the signal transduction of IL-4 and IL-13." (PMID 37240520, 2023). "This gene and its protein product were reported in relation to COVID-19, as IL4 is generally activated interleukin in bodily immune response to SARS-CoV-2 infection." (PMID 37795240, 2023). "In COVID-19 patients, significantly higher IL-4 lung tissue expression and M2 macrophages were observed, and the prevalence of IL-4 Th2-mediated lung damage was a characteristic of the ineffective immune response elicited by SARS-CoV-2." (PMID 36851291, 2023). "Accordingly, higher levels of IL-4 in the sera of COVID-19 patients positively correlates with both the time to viral clearance and severe illness." (PMID 37631998, 2023). "Cytokine concentration (TNF-alfa, IFN-gamma, IL-2, IL-4, IL-6, and IL-10) increased greatly after in vitro exposure to the COVID-19 vaccine." (PMID 37686102, 2023). "SARS-CoV-2 spike proteins that weigh less than 70 kDa can activate Th2 cells, generating a great deal of IL-4 and IL-13, which are elevated in both mild and severe COVID-19 patients." (PMID 37240520, 2023). "The cytokine IL-4 showed the highest activation score in the neutrophils of aged compared with young patients with COVID-19." (PMID 37606044, 2023). "We also report that the cytokine response was more diverse in COVID-19 patients, which is highlighted by IL-2, IL-4, and IL-20 signaling, while HIV-1+ individuals primarily exhibited high levels of NF-kB signaling." (PMID 36992700, 2023). "An analysis of cytokines Iraqi patients with COVID-19 demonstrated that the serum levels of IL-4 were significantly higher in patients with severe form of COVID-19." (PMID 37649897, 2023). "Both COVID-19 groups demonstrated a significant elevation (p < 0.001) in IL-1β, IL-4, IL-10, IL-17, and IFN-γ as compared to healthy controls." (PMID 35891209, 2022). "The expression of IL-4 in Tim-3+ NKT cells was significantly higher than Tim-3- NKT cells in deceased COVID-19 patients." (PMID 35250975, 2022). "The COVID-19 group had significantly higher plasma levels of IL-1β, IL-4, IL-7, IL-8, IL-12, TNF, IP-10, eotaxin, GM-CSF, bFGF, complement TCC and C3bc, and significantly lower levels of IL-13 and MIP-1α, as compared to controls." (PMID 35222429, 2022). "In terms of B cell modulation, the concentrations of BAFF and IFN-α were significantly higher and IL-4 lower in the entire patient group with COVID-19 (n = 110) compared to CKD patients." (PMID 36056305, 2022).
COVID-19 (continued). "In this meta-analysis, we analyzed serum levels of IL-1β, IL-2, IL-4, IL-6, IL-8, and IL-10 in COVID-19 patients with different disease severities." (PMID 35540724, 2022). "In this study, we identified that the serum levels of IL-6, IL-2R, IL-10, TNF-α, IL-1β, IL-4, IL-8 and IL-17 were significantly elevated in the severe or death cases and probably play crucial roles in the progression of COVID-19." (PMID 35237162, 2022). "In the primary infection COVID-19 patient cohort, several plasma proteins increase with COVID-19 disease severity, including IL-6, IL-8, IL-10, IL-4, and VEGF." (PMID 36679852, 2022). "IL-4 cells are formed from Th2 cells, which reportedly present in considerable quantities in COVID-19 sufferers." (PMID 35891209, 2022). "Nevertheless, in the present study, IFN-γ, IL-4, IL-5, IL-6, and IL-10 were the only cytokines elevated in patients with COVID-19." (PMID 34987205, 2022). "In contrast to moderate COVID-19 patients, severe COVID-19 patients had higher levels of IL-6, but IL-4, IL-18, and IL-35 between both illness categories were at close levels." (PMID 36675695, 2022). "Analyses of the cytokine concentrations in the sera of these volunteers indicated that COVID-19 patients presented a storm cytokine pattern with high levels of IL-4, IL-6 and IL-8 and low or insignificant levels of IFN-γ, as previously published." (PMID 35440789, 2022). "Controversial patterns were reported regarding IL-4 plasma levels where some reported an increase in peripheral blood/serum of severe COVID-19 patients, while studies show any difference." (PMID 35529862, 2022). "Significantly increased tissue immunoexpression of Arginase, CD4, CD68, CD138, Perforin, Sphingosine-1, and IL-4 markers were observed in the COVID-19 group." (PMID 36430210, 2022). "Higher concentrations of serological TNF-α, IL-6, MIP1b and IL-4 were observed within the P-COVID-19+ group, while cytokines and chemokines secreted by peripheral leucocytes in response to LPS, IL-6 or PMA-ionomicin were similar among the groups." (PMID 35901034, 2022). "IL-6 levels were greater in severe instances compared to moderate COVID-19 patients, but IL-4, IL-18, and IL-35 between both illness categories were at close levels." (PMID 36675695, 2022). "Time-adjusted differences in serum neopterin, β2M, TNF-α, IFN-γ, IL-4, and IL-2 were seen between the groups of patients with COVID-19, with higher concentrations found in neurosymptomatic patients." (PMID 35604688, 2022). "Our findings demonstrated that two groups of COVID-19 patients had significant increases in four pro-inflammatory cytokines (IL-1β, IL-6, and IL-18) and two anti-inflammatory cytokines (IL-4 and IL-35)." (PMID 36298501, 2022). "Pro-inflammatory cytokines IL-6, TNF-α, IL-8, IL-1α, anti-inflammatory cytokine IL-4, and the IP-10 chemokine were induced in the severe presentation of COVID-19 during pregnancy." (PMID 36016660, 2022). "Our results showed that serum IL-2, IL-4, IL-6, and IL-10 levels were elevated in COVID-19 patients compared to healthy controls, and IL-6, IL-8, and IL-10 levels were increased in severe COVID-19 cases compared to nonsevere patients." (PMID 35540724, 2022). "Serological TNF-α, IL-6, CCL4 and IL-4 levels were higher in P-COVID-19+ than in P-COVID-19-, although TNF-α was significantly higher in P-COVID-19+ than in P-COVID-19-." (PMID 35901034, 2022). "IL-4 continued to significantly increase in COVID-19 patients even several months after the onset of the disease." (PMID 35888019, 2022). "Supernatants were subsequently analyzed for key inflammatory cytokines associated with the cytokine storm in COVID-19 (IFN-γ, IL-1β, IL-2, IL-4, IL-6, IL-8, IL-10, IL-12p70, IL-13, and TNF-α), using the Meso Scale platform." (PMID 36296272, 2022). "We systematically searched records investigating the role of interleukins (IL-1β, IL-2, IL-4, IL-6, IL-8, and IL-10) in COVID-19 patients in Web of Science, Pubmed, and Embase through December 2020." (PMID 35540724, 2022).
COVID-19 (continued). "On the other hand, Th2 cytokine, IL-4, was positively correlated with serum urea, CK-MB, and troponin I in moderate COVID-19 patients and with urea, CK-MB, and LDH in severe cases." (PMID 35891209, 2022). "The receiver operator characteristic (ROC) curve analysis indicated that IL-1β, IL-4, IL-18, and IL-35 were fair (acceptable) predictors for COVID-19 in moderate cases." (PMID 36675695, 2022). "Overall, these findings identified the combined effect of elevated TNF-α, IFN-γ and IL-4 plasma levels in critically ill COVID-19 patients as some of the potent drivers of decreased antibacterial effector functionality of myeloid immune cells." (PMID 35007290, 2022). "The ratios of IL-12/IL-4, IL-12/IL-10, IL-12/IL-5, IL-12/IL-9, IL-2/IL-10, and IL-2/IL-9 were substantially higher in COVID-19 ICU patients compared with HC subjects (≈5660-, 5333-, 2100-, 600-, 69-, and 24-fold differences, respectively)." (PMID 36363785, 2022). "In most studies, compared with healthy controls, COVID-19 patients had significantly higher levels of interleukin (IL)-2, IL-4, IL-6, IL-10, tumor necrosis factor (TNF)-α, and C-reactive protein (CRP) and lower lymphocyte counts." (PMID 35310853, 2022). "The other anti-inflammatory cytokines IL-4 and IL-13 were raised only in recovered post-COVID-19 patients, whereas TGF-β1 remained unchanged in all cases." (PMID 36585712, 2022). "Our results indicated that serum levels of IL-2, IL-4, IL-6, and IL-10 were increased in COVID-19 patients compared to healthy subjects." (PMID 35540724, 2022). "Hematologic cancer patients that showed highly networked and coordinated anti-SARS-CoV-2 antibody production, with central importance of IL-4, IL-5, IL-12A, IL-15, and IL-17A, presented only mild COVID-19." (PMID 36700209, 2022). "The TNF-α, IL-6, MIP1b and IL-4 concentrations were higher in the P-COVID-19+ than the P-COVID-19- patients." (PMID 35901034, 2022). "On the other hand, the production of TH2 cytokines (IL-4 and IL-5) and IL-10 was poor or negligible in both post-COVID-19 patients and vaccinated subjects." (PMID 35744768, 2022). "On the other hand, anti-inflammatory cytokines such as IL-1Ra and IL-10 showed a sequential increase in mild-moderate and severe COVID-19, while IL-4 showed a significant increase in mild-moderate COVID-19." (PMID 35529862, 2022). "The COVID-19 group had significantly higher plasma levels of IL-1β, IL-4, IL-7, IL-8, IL-12, TNF, IP-10, eotaxin, GM-CSF, bFGF, and the complement activation products TCC and C3bc, as compared to the non-COVID-19 group." (PMID 35222429, 2022). "Studies on COVID-19 patients with severe respiratory symptoms have shown elevated serum levels of IL-4." (PMID 36363785, 2022). "In this study, we systematically analyzed the serum levels of IL-1β, IL-2, IL-4, IL-6, IL-8, and IL-10 in COVID-19 patients with different disease severities, as well as in healthy controls." (PMID 35540724, 2022). "In support, IL-4, IL-5, and IL-10 have previously been shown to increase over the course of disease in patients with severe COVID-19, suggesting an extensive upregulation of the adaptive immunity during COVID-19." (PMID 34987205, 2022). "IL-4, IL-7, IL-8, IL-12p70, IL-15, and VEGF were also associated with increased risk of intubation in COVID-19 subjects." (PMID 33995342, 2021). "When we analyzed the median proportion of selected cytokines levels (pg/mL) such as: IL-1β, IL-4, IL-5, IL-6, IL-8, IL-10 and TNFα, we observed significant difference between severe COVID-19 and critical COVID-19 patient only for IL-6 level." (PMID 34064802, 2021). "Cytokines rise in patients diagnosed with COVID-19, and the levels of IL-4 and sCD40L cytokines were higher in men than in women in our study." (PMID 35282595, 2021). "The frequency of Th17 cells (CD4+IL-17+) was reduced in both mild and severe COVID-19 group, whereas the frequency of Th2 cells (CD4+ IL-4+) was higher in both COVID-19 groups, compared to healthy donors." (PMID 33692788, 2021).
COVID-19 (continued). "A recent post-mortem analysis of lung biopsy samples of patients who died of SARS-CoV-2 showed significantly higher IL-4 tissue expression in COVID-19 patients compared both to H1N1 and control patients." (PMID 34685733, 2021). "Many cytokines in COVID-19 patients were significantly different from those in healthy individuals, including IL-2, IL-4, IL-6, CCL2, IFN-γ, and TNF-α." (PMID 34489974, 2021). "Early studies have demonstrated that asymptomatic or mild COVID-19 cases with immune skewing towards a systemic TH2 characterized by increases in IL-4 and IL-10." (PMID 34265022, 2021). "In contrast, COVID-19 was distinguished by a lymphocyte T cytokine response, as reflected by an increase in IL-2, IL-4, IL-5, IL-7, IL-13, IL-17, and soluble CD40L (sCD40L)." (PMID 35111777, 2021). "Our findings suggest that discharged patients continue to recover from the physiological effects of COVID-19, and the association of IL-4, IL-6, and IL-10 levels with metabolic changes and liver function repair may have important implications for clinical manifestations and treatment of COVID-19." (PMID 34307393, 2021). "One study out of six showed that the level of IL-4 in severe COVID-19 patients was significantly higher (3.3 ± 0.2 pg/ml) than in non-severe groups (3.4 ± 0.2 pg/ml)." (PMID 34046036, 2021). "In COVID-19 patients, the anti-inflammatory response mediated by molecules such as IL-10, IL-4 and TGF-β is finalized to balance the initial proinflammatory response described in several models." (PMID 34441796, 2021). "In this scenario, Th2 cells produce cytokines such as IL-4, -5, -10, and -13, which are significantly correlated with disease severity and mortality in COVID-19 patients." (PMID 35126355, 2021). "Last but not least, it is possible that IL-10 cooperates toward immunosuppression with other anti-inflammatory cytokines found increased in symptomatic COVID-19, such as IL-4, and IL-1RA." (PMID 33746948, 2021). "Our study showed that there was a good correlation between IL-2 and IL-4 in patients with COVID-19 or cancers." (PMID 34712741, 2021). "In both moderate and severe COVID-19 patients, the average concentrations of IL-4, IL-6, IL-10, CCL2, IFN-γ, and TNF-α (P<0.05) were higher than those in healthy donors." (PMID 34489974, 2021). "An increased immunoexpression of Sphingosine-1 (M2 Macrophages) and IL-4 in the COVID-19 group was observed, suggesting that the Th2 pathway was activated." (PMID 35008594, 2021). "Regarding Th2 cytokines, COVID-19 patients showed higher levels of IL-6, IL-10 and IL-13, but lower levels of IL-4 (p < 0.001, for all of them)." (PMID 33718270, 2021). "Nevertheless, IL-4, IL-5, and IL-13 displayed a trend toward an increase in the clinical scenario of severe COVID-19, and a reason for the interest is the importance of IL-5 to predict mortality, with a predictive value of around 0.73." (PMID 33767626, 2021). "The levels of IFN-γ and IL-4 were significantly lower in the recovery group than the severe case of the COVID-19 group." (PMID 33914789, 2021). "High levels of anti-inflammatory mediators, such as IL-10 and IL-4, have also been reported in COVID-19 patients, particularly ICU patients." (PMID 33640878, 2021). "The levels of IL-4 in sera of mild COVID-19 patients were slightly lower than in sera of healthy donors." (PMID 33692788, 2021). "IL-2 was lower in COVID-19 patients than in healthy individuals, while IL-4, IL-6, CCL2, IFN-γ, and TNF-α were higher in COVID-19 patients than in healthy individuals." (PMID 34489974, 2021). "In particular, higher levels of IL-4 have been reported in COVID-19 patients with more severe respiratory symptoms." (PMID 35126355, 2021). "Serum levels of IL-4 are observed to be much higher among COVID-19 patients compared to healthy controls." (PMID 35126355, 2021). "In our analysis, we found that IL12 levels remain low in patients with severe COVID-19 likely due to an increase in IL4." (PMID 34571891, 2021).